NANP (N-acetylneuraminic acid phosphatase)
Description:
Catalyzes the dephosphorylation of N-acylneuraminate 9-phosphate (Neu5Ac-9-P) to N-acetylneuraminic acid (Neu5Ac or sialic acid). Can also use N-glycoloylneuraminate 9-phosphate as substrate.
Synonyms: HDHD4; C20orf147; dJ694B14.3; MGC26833
Tractability: PROTAC: ubiquitination databases record sites on it.
Target class: Enzyme; Phosphatase
Gene: Protein-coding gene on chromosome 20 (25,612,935 to 25,624,014, reverse strand). Ensembl gene ENSG00000170191.
Subcellular location (Human Protein Atlas): Cytosol; Nuclear membrane
Pathways (Reactome):
Metabolism of proteins: Sialic acid metabolism
Gene Ontology:
Molecular function: N-acylneuraminate-9-phosphatase activity; hydrolase activity
Biological process: CMP-N-acetylneuraminate biosynthetic process; N-acetylneuraminate biosynthetic process; N-acetylglucosamine biosynthetic process; N-acetylneuraminate metabolic process
Cellular component: cytosol
Genetic constraint (gnomAD): Loss-of-function variants: 13 observed, 20.47 expected, observed/expected ratio (o/e) 0.64, 90% interval 0.41 to 1.01. The upper end of that interval is the gene's LOEUF score, 1.01, which puts it in group 4 of 6, group 1 being the genes least tolerant of losing a copy. Missense variants: 289 observed, 316.01 expected, observed/expected ratio (o/e) 0.91, 90% interval 0.83 to 1.01. Synonymous variants: 134 observed, 118.8 expected, observed/expected ratio (o/e) 1.13, 90% interval 0.98 to 1.3.
Homologues: Orthologues: chimpanzee NANP (99% identical), macaque NANP (99% identical), mouse Nanp (94% identical), pig NANP (94% identical), rabbit NANP (93% identical), dog NANP (91% identical), rat Nanp (85% identical), guinea pig NANP (81% identical), tropical clawed frog nanp (59% identical), zebrafish nanp (49% identical), Drosophila melanogaster CG15771 (31% identical). Paralogues in human: HDHD3 (20% identical).
Diseases named in the same sentence as NANP in open-access papers:
NANP is named in the same sentence as 12 diseases in open-access papers, as found by Europe PMC text mining. Sharing a sentence is not in itself a finding about the gene and the disease. The quoted sentences say what the papers report.
malaria (24 papers, 2012 to 2025). Malaria is a serious and sometimes fatal disease caused by a parasite that commonly infects a certain type of mosquito which feeds on humans. "Surprisingly, anti-NANP and anti-R21 IgM were also significantly associated with previous malaria exposure in children and infants." (PMID 40642064, 2025). "Specifically, 10 times increase in anti-NANP IgG concentration was associated with a decrease in malaria hazard by 33%." (PMID 31092823, 2019). "This functional activity was loosely associated with the magnitude and spread of NANP titres that also happen to be the best correlate of protection for CSP-based malaria vaccines in CHMI." (PMID 28288639, 2017). "We have shown that adults from a region of the malaria-endemic region have naturally acquired low levels of anti-R21, anti-NANP, and anti-C term antibodies." (PMID 40642064, 2025). "Given the moderate sensitivity of the assay for detecting malaria exposure based on antibody responses to CSP(NANP) and MSP-1 antigens, we sought to determine the sample size needed to implement this assay for serosurveillance purposes." (PMID 39852664, 2025). "In infants and children, previous malaria exposure (anti-schizont IgG) had a weak correlation that was significant with anti-full-length R21 and anti-NANP avidity." (PMID 40642064, 2025). "The results indicate that the repeat region of the CSP (NANP) is the strongest biomarker of exposure to P. falciparum-infected mosquitoes for this sample set, i.e., malaria-naïve individuals exposed once to Plasmodium-infected mosquitoes." (PMID 35407447, 2022). "Antibodies targeting the NANP/NVDP repeat domain of the Plasmodium falciparum circumsporozoite protein (CSPRepeat) can protect against malaria." (PMID 33852850, 2021). "Overall, the findings here should aid in defining the optimal characteristics of anti-NANP antibodies for therapeutic use, and also guide the design of more effective vaccines against malaria." (PMID 33594061, 2021). "After adjusting for anti-NANP IgG concentration, the correlation of C-term AI with malaria protection continued to be significant suggesting that the association was independent of the correlation between anti-C-term and anti-NANP responses." (PMID 31092823, 2019). "Increased continuous concentrations of NANP and C-term protected from first event of clinical malaria after adjusting for age and site, and results were comparable after adjusting for baseline levels." (PMID 31092823, 2019). "RTS,S vaccinees exhibiting M3 anti-NANP IgG concentrations at the lower tertile had significantly shorter median time to first clinical malaria event during 12 months of follow-up compared to vaccinees with intermediate or highest anti-NANP IgG concentrations." (PMID 31092823, 2019). "Collectively, these data show that NANP-specific antibodies were variably associated with C1q-fixation to CSP among individuals, and between the two malaria-endemic populations." (PMID 29706136, 2018). "Finally, the study also reported that the anti-NANP antibody titers were more than doubled in the R21/Matrix-M malaria group than in the RTS,S/AS01 (RTS,S) group after the third dose." (PMID 40563989, 2025). "After adjusting for anti-NANP IgG concentration, the correlation with protection from first and recurrent malaria events of anti-HBsAg IgG concentration continued to be strong suggesting that the association was independent of the correlation between anti-HBsAg IgG and anti-NANP IgG concentrations." (PMID 31092823, 2019). "Thus, focusing only on the size of the IgG anti-CSP NANP response may omit important correlates of protection against malaria." (PMID 37872492, 2023). "Responses to two antigens, the central repeat region of the circumsporozoite surface protein (CSP(NANP)) and the merozoite surface protein-1 (MSP1) showed significant differences between the IMRAS and CHMI, and the malaria-naïve controls." (PMID 39852664, 2025).
malaria (continued). "Antibodies against the NANP central repeat region of CSP have consistently been used as a measure of immunogenicity for the RTS,S/AS01 malaria vaccine as this is the primary target of the vaccine-induced humoral response." (PMID 37220123, 2023). "Reactivity of antibodies to the two CSP fragments (i.e., CSP.NANP, CSP.Cterm) was higher in samples from Uganda, indicating higher endemicity and prevalence of malaria." (PMID 35407447, 2022). "Altogether, these comprehensive characterizations of anti-NANP antibodies enhance our understanding of human humoral immune responses against CSP and provide a strong foundation for the design of next-generation malaria vaccines." (PMID 33594061, 2021). "The estimated anti-NANP antibody concentration in our VLPM01-immunized monkey serum was >200 μg/ml; therefore, we believe that VLPM01 is a promising malaria vaccine candidate." (PMID 28515133, 2017). "The anti-malarial antibody levels anti-AMA1 (Pf), MSP2 (Pf), NANP (Pf) and MSP1 (Pv) were significantly higher in people who had had malaria within the last 10 years." (PMID 22905743, 2012). "We note that the pattern of higher IgG, IgG1, and IgG4 levels to CSP FL and C-term in non-malaria cases was not apparent for NANP." (PMID 32550014, 2020). "In the C3C group, IgG and IgG1-3 to FL CSP and NANP were higher in the subjects with previous malaria cases but this difference was not statistically significant after adjusting for multiple testing." (PMID 32550014, 2020). "Machine learning multi-marker analyses revealed a signature of protection against clinical malaria in RTS,S vaccinees composed of antibodies to HBsAg (IgG3, IgG4, IgM, and IgG1 at M3 and M0, and IgG2 at M0), to CSP NANP (IgG3 at M3), and C-term (IgG1 and IgG at M3)." (PMID 30376866, 2018). "In contrast, IgG1 and IgG4 levels to NANP and CSP FL in the R3R group at M21 were lower in malaria cases, but not significantly." (PMID 32550014, 2020). "A significant increase in antibodies against Plasmodium falciparum antigens AMA1, MSP2, NANP and Plasmodium vivax antigen MSP1 in individuals with past history of malaria were observed when compared to those who did not." (PMID 22905743, 2012).
parasitemia (3 papers, 2013 to 2025). "Taken together, although the BDES vaccines delayed the appearance of blood stage parasitemia, the protective efficacy of the vaccines had no clear correlation with the anti-PfCSP Ab titers or with the anti-NANP titers." (PMID 23951015, 2013).
abscess (2 papers, 2011 to 2021). An inflammatory process characterized by the accumulation of pus within a newly formed tissue cavity which is the result of a bacterial, fungal, or parasitic infection or the presence of a foreign body. "The genotype of virulence factors in strain 20121 was plo/fimA/fimE/nanH/nanP, genes which have also been identified in bovine mastitis, pneumonia and abscesses, as well as encephalitis in goats." (PMID 35174243, 2021).
cervical cancer (1 paper, 2025). A primary or metastatic malignant neoplasm involving the cervix. "Future studies could further explore the specific mechanisms of NPL and NANP in cervical cancer and their potential as therapeutic targets." (PMID 40352586, 2025).
infection (6 papers, 2009 to 2025). The state of being infected such as from the introduction of a foreign agent such as serum, vaccine, antigenic substance or organism. "A recent paper reports for the first time on the association between anti-NANP IgG and infection efficacy in cohort 2 of this same trial." (PMID 20042088, 2009). "The colonization of host tissues in the first stage of infection is probably possible due to two neuraminidases, NanH and NanP." (PMID 39242520, 2024). "Mice immunization with Q11 fibrils, decorated with three tandem repeats of NANP sequence from Plasmodium falciparum, induces a potent anti-NANP IgG response and confers protection against infection with Plasmodium sporozoites in mice." (PMID 32466176, 2020). "Nevertheless, the available experimental human sporozoite challenge trial data for RTS,S with both AS01 and AS02 adjuvants is consistent with an important role of anti-NANP IgG in protection from infection." (PMID 20042088, 2009). "What can be deduced from the consistent pattern of associations seen for anti-NANP IgG and protection from infection with RTS,S, and the lack of association with morbidity to date?" (PMID 20042088, 2009). "These trends can be seen more clearly in a PCA using the three antigens that were found to be significantly different in the CHMI samples: gSG6-P1, reflecting the vector response; CSP.NANP, reflecting sporozoite exposure; and MSP-1, reflecting prior blood-stage infection." (PMID 35407447, 2022). "Infection studies conducted using mice or poultry have shown that inactivation of aroA in P. multocida strains X-73, P-1059, and 85020, tonB, exbB, and exbD in strain PM25, plpB in strain VP161, and nanP and nanU in strain P-1059 all resulted in reduced virulence." (PMID 41428671, 2025). "For CSP(NANP), a single five-bite exposure of sporozoites (likely delivering fewer than 1000 sporozoites) may not be sufficient to induce strong anti-CSP antibody responses, compared to repeated exposure over time in a natural infection setting." (PMID 39852664, 2025).
tumor (2 papers, 2021 to 2025). "Furthermore, the interaction between NPL and NANP may play a crucial role in the sialylation modification of tumor cells, affecting tumor cell invasion, metastasis, and immune evasion." (PMID 40352586, 2025). "We found that the sialic acid-donor synthesis pathway is particularly upregulated in PDAC, observing an increased expression of GNE, NANP and SLC35A1, suggesting a general increase of sialylation in the tumour." (PMID 33627655, 2021).
NANP also shares sentences with these, for which no sentence is quoted: Bovine mastitis (1 paper); cancer (1); encephalitis (1); mastitis (1); Pf (1); pneumonia (1).